PKHD1 (PKHD1 ciliary IPT domain containing fibrocystin/polyductin)
Diseases named in the same sentence as PKHD1 in open-access papers (continued):
Sharing a sentence is not in itself a finding about the gene and the disease.
colon cancer (4 papers, 2022 to 2025). "The results of this study indicate that PKHD1 somatic mutations are associated with worse overall survival outcomes in colon cancer patients, particularly when co‐occurring with other gene mutations." (PMID 38178618, 2024). "The current study investigated a cohort of 436 colon cancer patients and revealed that individuals with PKHD1 somatic mutations experienced significantly poorer overall survival outcomes compared to those without the mutation (p = 0.0058)." (PMID 38178618, 2024). "The study also highlights the prognostic significance of PKHD1 mutations in colon cancer patients, especially when co‐occurring with other gene mutations." (PMID 38178618, 2024). "A notable observation was the prevalence of PKHD1 mutations in the early stages of colon cancer, a trend that was corroborated by data from the TCGA COAD cohort." (PMID 38178618, 2024). "Utilizing two separate cohort studies, the present study provides an initial analysis focusing on characteristics including sex, age, and stage of cancer in relation to PKHD1 mutations in patients with colon cancer." (PMID 38178618, 2024). "We analyzed two colon cancer cohorts to discover the genetic and clinicopathological features of PKHD1‐mutated patients—data obtained from our in‐house clinical sequencing database and the Cancer Genome Atlas (TCGA)." (PMID 38178618, 2024). "We noted a higher frequency of PKHD1 mutations during the early stages of colon cancer, with a particular prevalence at stage 2." (PMID 38178618, 2024). "This suggests that the PKHD1 mutation may have an impact on the immune response and immune‐related pathways in colon cancer patients." (PMID 38178618, 2024). "PKHD1 somatic mutations may be a significant factor in determining overall survival outcomes in colon cancer patients, especially when co‐occurring with other gene mutations." (PMID 38178618, 2024). "Finally, the study reveals the distinct immune and microenvironment profile of PKHD1‐mutated patients, which may have implications for developing personalized immunotherapies for colon cancer patients." (PMID 38178618, 2024). "Overall, these findings suggest that PKHD1 may be a potential biomarker for the prognosis of colon cancer and provide some insight for personalized immunotherapy." (PMID 38178618, 2024). "These critical findings reinforce the potential of PKHD1 as a pivotal biomarker for colon cancer prognosis and may facilitate the emergence of personalized immunotherapy strategies." (PMID 38178618, 2024). "Notably, we observed that mutations in KRAS, PIK3CA, CREBBP, FAT1, PKHD1, ARID2, and POLE were specifically enriched in right-site colon cancers in both our cohort and the validation cohort." (PMID 36439454, 2022). "The results suggest that while the PKHD1 mutation status may serve as an important prognostic factor in colon cancer patients, it might not be an independent factor affecting overall survival outcomes." (PMID 38178618, 2024). "The current study could not thoroughly examine the impact of PKHD1 on colon cancer due to incomplete clinicopathological information in the data sets used." (PMID 38178618, 2024).
congenital hepatic fibrosis (4 papers, 2014 to 2023). "These include entities such as Caroli syndrome and congenital hepatic fibrosis which are most commonly associated with autosomal recessive polycystic kidney disease (ARPKD), secondary to mutations in the gene PKHD1 which encodes fibrocystin." (PMID 32432119, 2020). "HNF1B mutations can mimic ADPKD with important consequences for prognosis, the likelihood of comorbidities (for example, congenital hepatic fibrosis in PKHD1 or maturity onset diabetes of the young type 5 (MODY5) in HNF1B) and the risk of disease in siblings." (PMID 31118499, 2019). "The disease spectrum of clinical phenotypes caused by mutations in PKHD1 is relatively complex, ranging from perinatally-fatal ARPKD to Congenital Hepatic Fibrosis (CHF)-predominant presentations in adulthood with mild or no apparent kidney disease." (PMID 24710345, 2014).
glaucoma (3 papers, 2017 to 2026). Increased pressure in the eyeball due to obstruction of the outflow of aqueous humor. "For example, we show a remarkable long-range interaction leading to identification of the target gene TFAP2B for glaucoma-associated variant rs72904286 at the TFAP2B/PKHD1 locus." (PMID 36207300, 2022). "Here, we show that Pkhd1 del3-67/del3-67 mutant mice develop congenital glaucoma due to anterior segment dysgenesis." (PMID 41757104, 2026).
lung carcinoma (3 papers, 2009 to 2023).
cholangitis (2 papers, 2019 to 2024). An acute or chronic inflammatory process affecting the biliary tract. "Consequently, individuals with a family history of liver cirrhosis or recurrent cholangitis should be made aware of the importance of PKHD1 gene sequencing by healthcare professionals, in order to increase the early detection rate during check-ups." (PMID 38388441, 2024).
Obesity (2 papers, 2019 to 2023). Accumulation of substantial excess body fat. "The PKHD1 gene has been associated to T2DM, coronary artery disease, cardiac troponin T levels, and obesity-related traits." (PMID 37033211, 2023).
oligoamnios (2 papers, 2020 to 2024). "In this study, a heterozygous missense mutation (PKD1: c.6571C > T) in a fetus with bilateral echogenic kidneys and two frame shift deletions (PKHD1:c.8301del and c.4481del) in a fetus with bilateral hyperechogenic and enlarged kidneys combined with oligohydramnios were identified." (PMID 32779812, 2020).
renal carcinoma (2 papers, 2017 to 2019). A carcinoma arising from the epithelium of the renal parenchyma or the renal pelvis. "On the other hand, HNF1B is a transcription factor that acts as a tumor suppressor in renal carcinoma through control of PKHD1 expression." (PMID 30942869, 2019).
thyroid cancer (2 papers, 2019 to 2022). "Furthermore, MIR133B was found to inhibit PKHD1, which suppresses the proliferation of thyroid cancer cells and promotes the death of cancer cells, but its expression is low in early-stage PTC." (PMID 31126066, 2019).
anaplastic astrocytoma (1 paper, 2015). "In a dataset of anaplastic astrocytomas, mutations in two of these four genes (PKHD1 and MUC16) were identified and in a set of GBMs, mutations in three genes (MUC16, F5 and PKHD1) were identified." (PMID 26699864, 2015).
brain aneurysm (1 paper, 2023). A congenital or acquired aneurysm within the cranium. "Brain aneurysm was observed in eight patients (16%), and the causative genes were PKD1 (missense (n = 2), nonsense (n = 1)), PKD2 (missense (n = 1), splice-site (n = 1)), ZNF423 (missense), GLIS2 (missense) or PKHD1 (missense) or WDR19 (splice-site), and CEP164 (missense)." (PMID 36833371, 2023).
cardio-facio-cutaneous syndrome (1 paper, 2022). "Of the remaining five patients, three patients were found to have PKHD1 variants associated with autosomal recessive PKD (ARPKD), and two carried MAP2K2 variants associated with cardio-facio-cutaneous syndrome." (PMID 35099770, 2022).
cholangiocarcinoma (1 paper, 2024). A carcinoma that arises from the intrahepatic biliary tree (intrahepatic cholangiocarcinoma) or from the junction, or adjacent to the junction, of the right and left hepatic ducts (hilar cholangiocarcinoma). "In this study, the expression of PKHD1 was found to be significantly decreased in human cholangiocarcinoma tissues." (PMID 39512694, 2024).
colon adenocarcinoma (1 paper, 2024). "For the survival analysis of PKHD1 patients, survival data of 436 colon adenocarcinoma samples were obtained from TCGA dataset." (PMID 38178618, 2024).
congenital hypothyroidism (1 paper, 2022). A thyroid hormone deficiency present from birth. "The complication of congenital hypothyroidism might be associated with dyshormonogenesis in the thyroid due to PKHD1 gene mutations." (PMID 34536170, 2022). "RNA expression of the PKHD1 gene in the thyroid gland was low but detectable; therefore, we assumed that the dysfunctions of primary cilia due to PKHD1 gene mutation might lead to decreased follicular activity in the thyroid, which resulted in congenital hypothyroidism." (PMID 34536170, 2022). "More studies on primary cilia are needed to confirm the relationship between PKHD1 and congenital hypothyroidism." (PMID 34536170, 2022).
diabetic neuropathy (1 paper, 2023). A chronic, pathological complication associated with diabetes mellitus, where nerve damages are incurred due to diabetic microvascular injury involving small blood vessels that supply these nerves, resulting in peripheral and/or autonomic nerve dysfunction. "For diabetic neuropathy, gene GFY (rs4802605), ADH4 (rs4148883), LRFN2 (rs61731010), PKHD1 (rs2499486), SLC11A1 (rs17235409), MATN4 (rs2072788), and PPARA (rs4253772) were associated or contributed to the biological relevance to the pathogenesis of the complication." (PMID 37033211, 2023).
liver cancer (1 paper, 2022). An epithelial or non-epithelial malignant neoplasm that arises from the liver. "The mutation analysis was used to assess genetic variation of liver cancer, and it was found that PDE4DIP mutations were the highest in almost all patients with liver cancer, followed by SYNE1, KMT2C, PKHD1 and FN1." (PMID 35602894, 2022).
liver cirrhosis (1 paper, 2024). "The final diagnosis was based on the patient's family history of liver cirrhosis, biliary saccular dilation observed in imaging examinations, portal tracts fibrosis observed in liver biopsy, and the presence of PKHD1 mutation." (PMID 38388441, 2024).
mastitis (1 paper, 2023). Inflammation of breast tissue during lactation or postpartum due to an obstructed duct or infection. "Polycystic kidney and liver disease 1 (PKHD1), inducible T-cell co-stimulatory factor (ICOS), and cAMP-regulated phosphoprotein 21 (ARPP21) enhance mastitis resistance." (PMID 38028584, 2023).
multiple sclerosis (1 paper, 2016). A progressive autoimmune disorder affecting the central nervous system resulting in demyelination. "IL7R plays a role in the immune system and is implicated in multiple sclerosis, whereas PKHD1 influences kidney and liver functions." (PMID 27120335, 2016).
neuropathy (1 paper, 2023). A disorder affecting the nervous system that manifests with pain, tingling, numbness, and/or muscle weakness. "Interestingly, gene PKHD1 has been associated to intraocular pressure, brain measurement, T2DM, and metabolic markers, all risk factors associated to neuropathy." (PMID 37033211, 2023).
ovarian carcinoma (1 paper, 2006). A malignant neoplasm originating from the surface ovarian epithelium. "The specific role of TCF2 methylation in the development and progression of ovarian cancer remains unknown, but TCF2 mutations are known to affect expression of downstream genes such as HNF4α, PKHD1 and UMOD." (PMID 16479257, 2006).
rectal cancer (1 paper, 2024). A primary or metastatic malignant neoplasm that affects the rectum. "Therefore, future studies with a more complete set of clinical and pathomorphological data spanning colon and rectal cancers are essential to more fully elucidating the significance of PKHD1 mutations within the CRC landscape." (PMID 38178618, 2024).
schizophrenia (1 paper, 2023). A major psychotic disorder characterized by abnormalities in the perception or expression of reality. "Among highly ranked genes lacking SFARI Gene scores and OMIM annotations, previous studies suggest association with NDDs and schizophrenia [OBSCN, PLEC, RYR2, ZSWIM8], cortical formation and thickness [LAMA5, GOLGA3), and neurodegenerative diseases (PKHD1, DNAH1]." (PMID 35596027, 2023).
thyroid tumor (1 paper, 2022). A benign or malignant neoplasm affecting the thyroid gland. "We aimed to evaluate the common mutated genes (JMJD1C, MALAT1, MUC16, PDZD2, PKHD1, RYR1, SLA and TTN) between thyroid tumor and normal samples." (PMID 35996174, 2022).
kidney disease (16 papers, 2014 to 2025). "The patient's clinical findings of medullary nephrocalcinosis and diffuse liver cysts and his mild kidney disease are likely correlated with the monoallelic pathogenic PKHD1 variant." (PMID 37962562, 2024). "We provide a second case in a patient from Asia with liver and renal disease who carried the same paternally inherited missense PKHD1 mutation." (PMID 28814334, 2017). "Although the physiological function of FPC remains undefined, we anticipate that continued study of Pkhd1 mutant mouse models will expand our understanding of the mechanism(s) underlying mouse resistance to the severe renal disease that characterizes human ARPKD." (PMID 37584738, 2023). "Additionally, this is the second reported case to date of an Asian patient presenting with liver and renal disorders with the same paternally inherited PKHD1 missense mutation." (PMID 28814334, 2017). "In this particular case, the PKHD1 mutation only resulted in hepatic presentations without renal disorder." (PMID 38388441, 2024). "However, these orthologous mouse mutants, including the Pkhd1 knockout strain Pkhd1LSL/LSL17 (referred to as Pkhd1 KO) and the hypomorphic Pkhd1Δ3-4/Δ3-4 mutant carrying a deletion of exons 3–414,43, display minimal renal disease." (PMID 37845212, 2023). "A major obstacle to understanding normal FPC function and the pathogenic mechanisms that result from FPC deficiency is the lack of an orthologous animal model that fully recapitulates human PKHD1-associated renal disease." (PMID 36710876, 2022). "While the basis for PKHD1/Pkhd1 species–specific differences in renal disease expression is not understood, differences in the phenotypic severity between orthologous human disease and mouse models are not uncommon." (PMID 37584738, 2023).
cancer (13 papers, 2015 to 2024). A tumor composed of atypical neoplastic, often pleomorphic cells that invade other tissues. "Apart from SYNE1 and PKHD1 genes which were found to be maximally mutated to 22 other genes were identified as cancer driver genes which harbor 39 variants." (PMID 28324520, 2015). "The expression levels are very similar between sample groups and only the PKHD1 and LAMA1 genes have been implicated, so far, in cancer." (PMID 29844869, 2018). "In addition, this study conducted both univariate and multivariate Cox analysis to determine the significance of the PKHD1 gene mutation status in relation to other factors affecting overall survival, such as sex, MSI, age, TMB, and stage of cancer." (PMID 38178618, 2024). "PKHD1, which is mediated by receptor TNFRSF10B, mutates in PTC and induces expansion of the abnormality of the centrosome leading chromosome, which then leads to genome instability that could cause malignancy, promoting cancer cell proliferation and protecting cancer cells from apoptosis." (PMID 31126066, 2019). "Mutations in the PKHD1 and CDKN2A genes are not known to be cancer drivers in GBM according to the TCGA." (PMID 32041307, 2020). "Moreover, signaling transduction protein PKHD1, which was mediated by receptor TNFRSF10B, could induce cancer cell proliferation and suppression of cancer cell apoptosis by the occurrence of genetic mutation and translocation." (PMID 31126066, 2019). "PKHD1 appeared in ESCC and SCLC lists but in none of the common cancer gene lists, suggesting some molecular commonalities between ESCC and SCLC." (PMID 29050228, 2017).
tumor (12 papers, 2017 to 2025). "In this study, immunohistochemistry was used to detect the expressions of EMT-related protein MMP9 and Snail in the PKHD1(-/+) and the normal control tumor-bearing mice." (PMID 39512694, 2024). "The results of subcutaneous tumor implantation in nude mice suggested that the growth rate, volume, and weight of tumors in the PKHD1(-/+) group was significantly increased compared to the CTRL group (P< 0.001)." (PMID 39512694, 2024). "To further investigate the relationship between KIRP tumor immunity, we performed the correlation analysis between KIRP immune checkpoint genes (CTLA4, HAVCR2, PDCD1, PDCD1LG2, and TIGIT) and high mutation frequency genes (TTN, MET, KMT2C, PKHD1, SETD2, and KMT2D)." (PMID 36618928, 2022). "The differentially expressed genes in triphasic tumours relative to blastemal tumours included genes published as potential UB/CD markers: MUC1, PKHD1, KRT7, CDH1, and LIF." (PMID 29040332, 2017).
kidney (8 papers, 2016 to 2025). "Fibrocystin (FPC) is a protein encoded by the polycystic kidney and hepatic disease 1 (PKHD1) gene, whose mutation results in ARPKD." (PMID 40136708, 2025). "Familial clusters suggest a potential genetic basis, with the polycystic kidney and hepatic disease 1 (PKHD1) gene most commonly associated." (PMID 39534797, 2024). "The disorder is caused by mutations in the polycystic kidney and hepatic disease 1 (PKHD1) gene, which encodes fibrocystin (also known as polyductin), a protein localized in the primary cilium and basal body." (PMID 34876198, 2021). "To elucidate the mechanisms underlying the genetic interaction between Pkhd1 and Pkd1 in kidney cystogenesis, we examined whether the loss of FPC alters the expression and cleavage of PC1." (PMID 37845212, 2023). "A substitution in an intron in the polycystic kidney and hepatic disease 1 (PKHD1) gene (rs41641297) and a SNP (rs110742604) positioned in regulatory regions of TUBB5 and FLOT1 genes." (PMID 29439661, 2018). "Microsatellite maker testing at the polycystic kidney and hepatic disease 1 (PKHD1) locus (6p12.2) was undertaken using a custom multiplex mix for the gene and flanking microsatellites." (PMID 27461731, 2016).
genetic disease (4 papers, 2017 to 2023). "The mutation in this case help to understand the relationship between genotype of PKHD1 gene and phenotype of ARPKD, and WES is suitable for genetic diagnosis of inherited diseases like ARPKD." (PMID 32481435, 2020).
infection (2 papers, 2016 to 2025). The state of being infected such as from the introduction of a foreign agent such as serum, vaccine, antigenic substance or organism. "Additionally, genes involved in calcium signaling and ion channel regulation—PKD1, PKHD1, TRPC1, TRPM6, and TRPM7—highlight the importance of cellular homeostasis and signaling during infection." (PMID 41114509, 2025). "However, the expression of Pkd2, Pkhd1, Kif12, Cadherin16 and Socs3, which are known as HNF-1β target genes, did not change (data not shown), and only a few genes, including NR1H4, MITF, SLC3A1, and SLCO4C1, were significantly upregulated 9 h after Ad-HNF1B infection." (PMID 27196561, 2016).